WNT5A (Wnt family member 5A)
Diseases named in the same sentence as WNT5A in open-access papers (continued):
Sharing a sentence is not in itself a finding about the gene and the disease.
prostate carcinoma (continued). "To investigate whether there is an interaction between EZH2 and WNT5A in prostate cancer, we transfected C4-2B EnzR cells with siEZH2, siSFRP1, and their negative controls." (PMID 38566211, 2024). "Wnt5a from the bone microenvironment also induces prostate cancer dormancy." (PMID 37464317, 2023). "Protein Wnt-5a (Wnt5a) expression in the osteoblastic niche has been found to promote dormancy in a model of prostate cancer via the activation of the Wnt5a/tyrosine-protein kinase transmembrane receptor ROR2 (ROR2)/E3 ubiquitin-protein ligase SIAH2 (SIAH2) signalling axis." (PMID 36701089, 2023). "Furthermore, RT-qPCR showed that WNT5A mRNA levels were decreased in PC3-shESS2 cells, and a correlation was observed between ESS2 and WNT5A expression in patients with prostate cancer." (PMID 37524814, 2023). "WNT5A mediates the activation of Tregs and tumor-associated macrophages (TAM), which thereby induces immunosuppression during the progression of castration-resistant prostate cancer." (PMID 35686121, 2022). "Intriguingly, an enzyme-linked immunosorbent assay (ELISA) detected a two-fold increase in Wnt5a in the femur when compared to the humerus and knockdown of WNT5a in a bone marrow stromal cell line (HS-5) significantly reduced LNCaP and PC-3 prostate cancer cell invasion in vitro." (PMID 35204808, 2022). "Conditioned media from bone marrow-derived mesenchymal stem cells MC3T3-E1 and hFOB1.19 rich in Wnt5a can also induce prostate cancer cell dormancy, indicating Wnt5a is secreted from a plethora of cell types within the bone microenvironment to promote dormancy of disseminated tumor cells." (PMID 35204808, 2022). "WNT5A gene is a tumor suppressor gene for various cancers but a protooncogene for prostate cancer." (PMID 36553576, 2022). "This indicates that Wnt5A acts as a chemoattractant to promote metastasis of prostate cancer cells." (PMID 35927755, 2022). "Further, using mouse models, ectopic expression of Wnt5a attenuated the effects of an AR inhibitor and suppression of Wnt5a could partially restore the sensitivity in drug-resistant prostate cancer cells." (PMID 34803167, 2021). "RYK is one of the receptors for Wnt family member 5A (WNT5A) and has been reported to be involved in invasive activity in glioma-derived cells and to facilitate the pro-apoptotic and anti-proliferative effects of WNT5A in prostate cancer cells." (PMID 34437536, 2021). "Wnt5a acts as a tumor suppressor gene for several cancers but a protooncogene for prostate cancer." (PMID 35201496, 2021). "Furthermore, Foxy-5, a peptide derived from the same region of Wnt5a as UM206, has been shown to reduce metastatic spread of prostate cancer cells, underscoring the pharmacological potency of Wnt5a fragments." (PMID 31620445, 2019). "In prostate cancer we showed that WNT5A exerts anti-tumor effects." (PMID 29930766, 2018). "Moreover, FZD5 and WNT5A co-expression exhibits potential as disease specific survival marker for prostate cancer patients." (PMID 29930766, 2018). "By analyzing the expression of known WNT5A receptors in five different prostate cancer cell lines, performing functional assays, and validating receptor expression in a large set of human samples, we found the receptors FZD5 and RYK mediate anti-tumor effects of WNT5A in prostate cancer." (PMID 29930766, 2018). "The same work also demonstrated the existence of calcium waves that are induced by WNT5A in cultured metastatic prostate cancer cells, as well as this protein’s stimulation of the actin cytoskeleton activity and cell motility (the latter being also under the control of CAMKII)." (PMID 29671777, 2018). "Further pointing to an explanation whereby the WNT-β-catenin signaling in prostate cancer development may be stage-specific is the finding that the WNT5A protein is upregulated specifically in the metastatic human samples." (PMID 29671777, 2018).
prostate carcinoma (continued). "Moreover, we have previously shown that FZD5 mRNA expression is upregulated in human prostate cancer and correlates with WNT5A expression." (PMID 29930766, 2018). "Activation of the Canonical Wnt pathway (CWP) has been linked to advanced and metastatic prostate cancer, whereas the Wnt5a-induced non-canonical Wnt pathway (NCWP) has been associated with both good and poor prognosis." (PMID 28030815, 2017). "Thus, our study further supports the use of Foxy-5 as a future treatment for prostate cancer patients that lack or show reduced endogenous expression of WNT5A in their primary tumor." (PMID 28886116, 2017). "Importantly, our present results lend direct support to recent findings implicating WNT5A in the suppression of prostate cancer metastases through a complex network of signaling proteins, including Snail, Cyclin D1 and c-Myc." (PMID 28886116, 2017). "Nevertheless, the identification of WNT5A as an ERRα-regulated gene may represent implications for its potential use as a prognostic marker in prostate cancer." (PMID 27776343, 2016). "Another study on prostate cancer showed that Wnt5a bound to Fzd2 and Ror2 and activated JNK signaling, leading to expression of matrix metalloproteinase 1 (MMP1) through enhancing the recruitment of JunD to the AP-1 site of MMP1 promoter region, thereby inducing cell migration and invasion." (PMID 27571105, 2016). "Prostate cancer tissues show increased expression of WNT-5A promoting migration and invasiveness." (PMID 26514730, 2016). "Moreover, bone marrow stromal cells secreted Wnt5a, which enhanced the migration of prostate cancer cells towards bone marrow stromal cells, suggesting a role of Wnt5a as a chemoattractant that induces prostate cancer metastasis to the bone." (PMID 27571105, 2016). "A recent study showed that Wnt-5a promotes the aggressiveness of prostate cancer." (PMID 22325146, 2012). "It has also been reported that Wnt5a expression is of clinical relevance in prostate cancer." (PMID 23076981, 2012). "In addition, we carried out immunocytochemistry of Wnt5a in prostate cancer cell lines (LNCaP, 22Rv1 and DU145) after pretreatment with either scrambled or Wnt5a si-RNA." (PMID 22039506, 2011). "First, we observed cytosolic staining of Wnt5a similar to that observed in the prostate cancer tissue and secondly, the intensity of Wnt5a immunostaining decreased significantly in the Wnt5a si-RNA treated cells compared with those treated with scrambled si-RNA." (PMID 22039506, 2011). "However, important questions regarding Wnt5A expression and the mechanisms of Wnt5A mediated signaling in prostate cancer remain." (PMID 20454608, 2010). "WNT5A transcript is also expressed in other prostate cancer cell lines e.g. PC3 and DU145." (PMID 20454608, 2010). "Similarly to WNT5A, Foxy5 reduced the migration and invasion of breast and prostate cancer cells." (PMID 37998393, 2023). "Thus, our results showed that ESS2-dependent WNT5A expression may affect prostate cancer progression." (PMID 37524814, 2023). "Similarly, a recent report found that Wnt5A induces the dormancy of prostate cancer cells in bone." (PMID 34685470, 2021). "Moreover, WNT5A may be involved in the regulation of prostate cancer cells adhesion, as already shown in several other tumors." (PMID 28886116, 2017). "Furthermore Wnt5a induced the expression of metalloproteinase-1 (MMP-1) in prostate cancer." (PMID 23383207, 2013). "We next tested the following hypotheses: (i) inhibition of CaMKII should disrupt the wound leading edge in prostate cancer cell lines (ii) activation of Wnt5A signaling in 1542-NPTX cells should promote actin remodeling of the wound as observed in 1542-CP3TX cells." (PMID 20454608, 2010). "ESS2 tends to be highly expressed in prostate cancer patients, and expression levels of some ESS2 target genes, such as LIF, WNT5A, and TGFB1, were significantly correlated with ESS2 levels in prostate cancer patients." (PMID 40362295, 2025).
prostate carcinoma (continued). "Microarray analysis revealed that ESS2 regulated mRNA levels of chromodomain helicase DNA binding protein 1 (CHD1)-related genes and other cancer-related genes, such as PPAR-γ, WNT5A, and TGF-β, in prostate cancer." (PMID 37524814, 2023). "In prostate cancer, WNT5A recruits and regulates macrophages through CCL2 to induce castrated prostate cancer." (PMID 35847885, 2022). "The Wnt ligand secretion mediator wntless (WLS) has also been shown to confer enzalutamide resistance in prostate cancer cells, and Wnt target genes LEF1 and WNT5a are elevated in LNCaP-AI cells (cultured in androgen-depleted media)." (PMID 35204808, 2022). "Wnt5a promotes liver fibrosis by FZD2 and FZD8 42, and Wnt11 binds to FZD8 known to be involved in TGF-β signaling in prostate cancer." (PMID 33391533, 2021). "Wnt5A was found to recruit and regulate bone marrow macrophages through the subsequent secretion of CCL2 and BMP6, which aided in the development of prostate cancer castration resistance." (PMID 34685470, 2021). "In conclusion, WNT5A/FZD5 and WNT5A/RYK signaling are both involved in mediating the pro-apoptotic and anti-proliferative effects of WNT5A in prostate cancer." (PMID 29930766, 2018). "To determine which receptors mediate the anti-proliferative and pro-apoptotic effects of WNT5A in prostate cancer, we knocked-down each of the receptors with specific siRNAs in PC3 cells 24 h before the induction of WNT5A overexpression." (PMID 29930766, 2018). "These indications prompted us to test the effect of the WNT5A agonist Foxy-5 on the invasion of both DU145 (with a low endogenous expression of WNT5A) and PC3 prostate cancer cells (with high endogenous level of WNT5A)." (PMID 28886116, 2017). "Wnt-3a and Wnt-5a administration or knockdown of DKK-1 induced BMP-4 and 6 expression and promoter activation in prostate cancer cells." (PMID 22325146, 2012). "Our results showed lower expression of Wnt pathway-related proteins—β-catenin, Fzd8, Wnt5a and cyclin D1—in prostate cancer compared to BPH tissues, but the differences were not statistically significant." (PMID 41465498, 2025). "The non-canonical Wnt ligand Wnt5a, secreted by osteoblasts in the endosteal niche, induces and maintains prostate cancer cell dormancy via the activation of non-canonical Wnt signaling, resulting in the suppression of the canonical Wnt pathway." (PMID 36497192, 2022). "In support of the non-canonical Wnt ligand Wnt5a playing an oncogenic role in prostate cancer, Wnt5a depletion in the TRAMP mouse model of neuroendocrine prostate cancer harboring an ART877A mutation suppresses tumor onset and progression." (PMID 35204808, 2022). "Knockdown of RYK in PC-3 prostate cancer cells reduces Wnt5a-induced apoptosis in vitro without altering proliferation via an unclear mechanism." (PMID 35204808, 2022). "Especially for prostate cancer, investigators have shown the importance of the non-canonical ligand Wnt5A for CTC function." (PMID 34685470, 2021). "Our previous work identified LGALS3, KLF4, and non-canonical WNTs (i.e., WNT5A), as genes enriched in CTCs from overtly metastatic pancreatic, breast, and prostate cancer mouse models and patients." (PMID 32620742, 2020). "It has been demonstrated that ERRα expression is correlated with castration-resistant prostate cancer, and it could promote tumor progression by targeting a number of cancer-related genes, including VEGF-A, WNT5A and TGFβ1, and WNT11 and HIF-1α." (PMID 33014785, 2020). "In prostate cancer cells, ECM-deposited latent TGFβ can be activated by membrane type I-matrix metalloprotease (MT1-MMP/MMP14), which then induces the secretion of Wnt5a; the sequential action of TGFβ and Wnt5a sustain EMT and invasiveness of the tumor cells." (PMID 30463358, 2018). "miR-26a suppresses WNT-5A and forced expression of miR-26a attenuates cell proliferation, metastasis, and EMT, and induced G1 phase arrest suppressing WNT-5A expression and inhibiting prostate cancer progression." (PMID 26514730, 2016).
prostate carcinoma (continued). "Prostate cancer cells show increased migration towards bone marrow stromal cells which is suppressed in the presence of WNT-5A siRNA-transfected bone marrow stromal cells, suggesting that WNT-5A can also function as a chemoattractant or homing factor for prostate cancer cells." (PMID 26514730, 2016). "In the previous study, increased Wnt5A, β-catenin and VEGF-A were found in non-small-cell lung cancer (NSCLC), and Wnt5A expression was correlated to expression of VEGF, Ki67, androgen receptor in prostate cancer." (PMID 25401518, 2014). "Based on these findings, an ongoing phase 1 study is being conducted to evaluate the safety and tolerability of treatment with Foxy-5 in patients with metastatic breast, colorectal, or prostate cancer, and only Wnt5a-negative or Wnt5a-low patients are enrolled in the study." (PMID 33126517, 2020). "Similarly, ROR2 was not differentially expressed in healthy and primary prostate cancer tissue and did not correlate with WNT5A expression." (PMID 29930766, 2018). "To conclude, our data indicate that the WNT5A-mimicking peptide Foxy-5, which has been recently used in a phase 1 clinical trial, is an attractive candidate for complimentary anti-metastatic treatment of prostate cancer patients with tumors exhibiting absent or low WNT5A expression." (PMID 28886116, 2017). "Consequently, the group of prostate cancer patients that would most highly benefit from the reconstitution of WNT5A functions is the one that includes patients with absent or low WNT5A expression in their tumors." (PMID 28886116, 2017). "Therefore, ROR2 may not mediate the anti-tumor effects of WNT5A in primary prostate cancer, but may have a more significant role in metastasized prostate cancer stages." (PMID 29930766, 2018). "The canonical Wnt ligand Wnt3a and the non-canonical ligand Wnt5a were shown to induce BMP-4 and -6 expression in prostate cancer and to stimulate osteoblast differentiation that resulted in osteoblastic lesion formation." (PMID 36497192, 2022). "WNT-5A induced BMP-6, thus contributes to the proliferation of prostate cancer cells in the absence of androgens." (PMID 26514730, 2016). "The non-canonical Wnt ligand Wnt5a, which may regulate cellular motility via the Wnt-PCP pathway, was shown to promote the homing of prostate cancer cells to bone." (PMID 36497192, 2022). "However, Wnt5a has also been reported to play an opposing tumor-suppressive role by abrogating the YAP/TAZ pathway, as evidenced by its negative feedback in the ROR2-YAP/TAZ pathway in a prostate cancer model." (PMID 40542295, 2025).
lung cancer (63 papers, 2006 to 2025). A malignant neoplasm involving the lung. "Cigarette smoke is associated with 90% of lung cancer (Ozlü & Bülbül, 2005) and persistent cigarette smoke polarises lung macrophages to an M1 phenotype via a Wnt family member 5a dependent pathway." (PMID 35415881, 2022). "In lung cancer, dysregulation of Wnt signaling has been found, and overexpression of Wnt proteins (Wnt1 and Wnt5a) was notably linked to unfavorable overall survival in lung cancer patients." (PMID 31775307, 2019). "Our prior meta-analysis demonstrated that the overexpression of Wnt proteins (Wnt1 and Wnt5a) was notably linked to unfavorable overall survival in lung cancer patients." (PMID 28646916, 2017). "We then evaluated the association between Wnt5a expression and smoking exposure using 12 lung cancer samples and matching normal tissues (7 from smokers and 5 from non-smokers)." (PMID 23349696, 2013). "We investigated the associations between Wnt5a and the early development of cigarette smoke related lung cancer using human bronchial epithelial (HBE) cells (NHBE, BEAS-2B, 1799, 1198 and 1170I) at different malignant stages established by exposure to cigarette smoke condensate (CSC)." (PMID 23349696, 2013). "Thus, we examined the association between Wnt5a and lung cancer in 1799 cells using CSC which contains most of the compounds of cigarette smoke." (PMID 23349696, 2013). "Moreover, the tumors were acquired from lung cancer patients with squamous cell carcinoma, implying possible association between Wnt5a expression and tumor histology like as a previous report." (PMID 23349696, 2013). "Furthermore, whether EGFR/ERK1/ERK2 or WNT1/WNT5A/WNT7B gene expression was potentially associated with the OS of lung cancer patients was assessed by Kaplan-Meier curve and Log-rank test." (PMID 34122668, 2021). "In the context of lung cancer and inflammation in RA, the Wnt5a signaling pathway seems to be a potential molecular link, given its involvement in both oncogenic processes and chronic inflammation." (PMID 40282506, 2025). "As indicated in the Results section, we evaluated those targets in our experimental system and found that GLUT1, NRP1, YY1, and Wnt5a were effectively inhibited by the miRNA in lung cancer cells." (PMID 38672608, 2024). "BRD4 mRNA was positively correlated with Wnt5a and NF-κB2 mRNAs in lung cancer tissues in the TCGA cohort." (PMID 38229152, 2024). "Previous studies have demonstrated that activated Yap, through genetic amplification of YAP- or WNT5a-mediated dysregulation of the Hippo pathway, enables bypass of Kras suppression in Kras-driven murine pancreatic cancer and lung cancer models." (PMID 39704172, 2024). "This interaction reduces the miRNA silencing activity toward its downstream targets, i.e., the mRNAs coding for GLUT1, NRP1, YY1, and Wnt5a, thus contributing to oncogenic pathways driving lung cancer." (PMID 38672608, 2024). "Inhibition of Wnt signaling pathway activation enables miR-4757-3p to regulate Wnt5a and Wnt8b genes to stimulate cell invasion and migration in lung cancer." (PMID 36814555, 2023). "In fact, Fzd2 and Wnt5a/b (among 10 Fzds and 16 Wnts) are known to be expressed at higher levels in several metastatic cancer cells, including lung cancer cells." (PMID 37703992, 2023). "In human lung cancer, the main Wnt ligands are Wnt1, Wnt2, Wnt5a, and Wnt7a, and an increase in Wnt proteins, Wnt1 or Wnt5a alone, is significantly related to poor prognosis in NSCLC." (PMID 35719973, 2022). "Our study indicated that sevoflurane inhibited the proliferation, and invasion, but enhanced the apoptosis in lung cancer cells by regulating the lncRNA PCAT6/miR-326/Wnt5a/β-catenin axis." (PMID 33987473, 2020). "Upregulation of WNT5A increases EMT in lung cancer possibly through stimulation of the non-canonical PKC Wnt pathway." (PMID 31694854, 2020).